PTN (pleiotrophin)
Diseases named in the same sentence as PTN in open-access papers (continued):
Sharing a sentence is not in itself a finding about the gene and the disease.
tumor (continued). "On the other hand, alterations in PTN are related to tumor cell proliferation and prognosis of neoplasms, such as glioblastoma, testicular germ cell neoplasms, and hepatocellular carcinoma." (PMID 37443767, 2023). "In HER2low TNBC group, the fate 1 branch was predominantly associated with module 2 genes (PTN, KRT15, S100A8, etc.)which suggested the tumor harbored the features of apoptosis, migration and metabolism." (PMID 36998014, 2023). "Additional factors that are expressed in BC tissues in a fashion that positively correlates with both the intensity of angiogenesis and tumor aggressiveness include TGFβ-1, pleiotrophin, placental growth factor, and PDGF." (PMID 36834641, 2023). "Such as macrophage migration inhibitor (MIF), polytrophic factor (PTN) and cell adhesion related genes (cadherin, cadherin-1 and desmosomes) are highly expressed in the signaling pattern of tumor cells." (PMID 37213285, 2023). "All but one (ARG1) of the proteins with significantly lower expression at baseline in the p16+ tumour group also showed lower expression at 12 months—that is, PTN, TNFRSF12A, CD28, and CD70." (PMID 36835246, 2023). "Transfection of HBV plasmid into non-HBV-related HCC cells significantly promoted the activity of PTN in tumor cells." (PMID 37259127, 2023). "This analysis suggested neoplastic tumor cell PTPRZ1 targeting by PTN, the latter largely produced by the neoplastic cells." (PMID 36966348, 2023). "PTN IHC staining of lymph nodes and tumor tissue from patients with LN+ and LN− disease revealed that PTN expression was significantly higher in lymph nodes as well as in tumors from LN+ patients." (PMID 36828390, 2023). "PTN, a growth factor, plays an important role in nervous system development, tumor angiogenesis and growth, wound repair, and other disease phenotypes." (PMID 36082132, 2022). "Pleiotrophin secreted by TAMs was shown to promote PTPRZ1 signaling in GBM stem cells leading to tumor growth." (PMID 36712881, 2022). "The results showed that APOD, DCN, and PTN were downregulated in tumor samples compared with normal samples." (PMID 35420507, 2022). "Upregulation of PTN by activating the NF- κ B pathway promotes tumor cell proliferation, inhibits apoptosis and chemosensitivity." (PMID 35281077, 2022). "Co-implantation of M2-like macrophages (MLCs) promoted GSC-driven tumor growth, but depletion of PTN expression in MLCs mitigated their pro-tumorigenic activity." (PMID 35600367, 2022). "By contrast, the PTN-PTPRZ1 RNAscope assays indicated higher levels of autocrine signaling in regions of dense tumor, evidenced by a nearly fourfold drop in double-positive cells when comparing regions in the cellular tumor to adjacent tissue." (PMID 36539501, 2022). "While the frequency of cells expressing PTN increased in the transition from tumor to adjacent tissue, the frequency of cells expressing PTPRZ1 decreased in an anticorrelated fashion." (PMID 36539501, 2022). "Upregulated PTN promoted tumor cell proliferation and inhibited apoptosis and chemosensitivity by activating the NF-κB pathway." (PMID 33833937, 2021). "Single studies concerning various cancers showed that Pro-NGF/NGF (nerve growth factor), BDNF (brain-derived neurotrophic factor), Ephrin B1, neuroligin-3, pleiotrophin, semaphorin 4F were involved in the regulation of tumor innervation." (PMID 34277455, 2021). "In contrast to SETMAR protein isoforms, snRNP70, OLIG2 and PTN protein levels were lower inside the necrotic area, while being detected at higher levels within the tumor region." (PMID 35047379, 2021). "Meta-analysis showed that high expression of PTN was significantly associated with an advanced TNM stage and a poor OS in tumor patients." (PMID 33833937, 2021). "MDK and PTN interact with a plethora of surface receptors to initiate tumor promoting cell motility/invasion, survival, and drug resistance." (PMID 34502484, 2021).
tumor (continued). "The PTN gene is highly expressed in several tumor cell types involved in tumor angiogenesis and presents mitogenic activity for fibroblasts." (PMID 32168333, 2020). "RNA pulldown and luciferase assays showed that MACC1-AS1 contained binding sites for multiple miRNAs, including well-known tumor suppressors miR-384 and miR-145-3p that repress the expression of pleiotrophin (PTN) and c-Myc mRNAs." (PMID 31822653, 2019). "Pleiotrophin is a secreted cytokine related to diverse biological properties, including neuritis outgrowth, angiogenesis, and tumour growth." (PMID 30635982, 2019). "It is strongly expressed in different human tumour cells, and expression of the PTN gene in tumour cells in vivo accelerates growth and stimulates tumour angiogenesis." (PMID 30635982, 2019). "Enhanced secretion of pleiotrophin, one of the extracellular ligands of PTPRZ abundantly expressed in GBM tissue, from tumor-associated macrophages in GBM tissue promotes tumor growth of GBM stem cells." (PMID 30791455, 2019). "Further studies are needed to clarify the precise role of PTN in tumor growth, and more large‐scale prospective studies are needed to confirm this finding." (PMID 30635982, 2019). "The aim of this meta-analysis is to explore the prognosis and clinicopathological factors of pleiotrophin (PTN) in tumor patients considering the possible deviations of individual studies." (PMID 30427932, 2018). "Our meta-analysis indicated that the high expression of PTN was remarkably associated with advanced TNM stage (OR = 2.79, 95%CI: 1.92–4.06, P<0.00001) and poor OS (HR = 1.77, 95%CI: 1.41–2.22, P<0.00001) in tumor patients." (PMID 30427932, 2018). "Some researchers reported that pleiotrophin (PTN) is associated with the development and metastasis of various tumors and it is a poor prognostic factor for the tumor patients." (PMID 30427932, 2018). "The tumor patients in all of the ten researches were separated into two groups (PTN high expression group and PTN low expression group)." (PMID 30427932, 2018). "PTN has been confirmed to be upregulated in some types of cancers and to play an important part in tumour angiogenesis and metastasis." (PMID 30427932, 2018). "The number of patients with tumor size was reported in six studies in view of different PTN expression levels, totally including 532 patients." (PMID 30427932, 2018). "In conclusion, our findings underscore the crucial role of the PTN–PTPRZ1 paracrine signalling as a molecular link to mediate the tumour-supportive effects of M2 TAMs on GSC maintenance and GBM malignant growth." (PMID 28569747, 2017). "We found that the tumour areas with more Iba1+ TAM infiltration showed more PTN staining (P<0.01, Student's t-test)." (PMID 28569747, 2017). "After DOX treatment, PTN knockdown significantly inhibited xenograft tumor growth (p=0.009), while PTN overexpression enhanced tumor growth (p=0.025)." (PMID 28969035, 2017). "Taken together, these data demonstrate that the M2 TAM-secreted PTN is a crucial paracrine factor in mediating the tumour-supportive effect of TAMs to promote GSC tumour growth." (PMID 28569747, 2017). "Co-implantation of M2-like macrophages (MLCs) promoted GSC-driven tumour growth, but silencing PTN expression in MLCs mitigated their pro-tumorigenic activity." (PMID 28569747, 2017). "Our study suggests another potential strategy to compromise the tumour-supportive functions of TAMs by disrupting the TAM-paracrined PTN signalling." (PMID 28569747, 2017). "Consistent with the results obtained in vitro, the tumour volume and tumour weight in the PTN overexpression group were significantly greater than those in the control group." (PMID 28557334, 2017). "To interrogate the impact of the PTN–PTPRZ1 signalling on GSC-driven tumour propagation, we examined the effect of PTPRZ1 disruption on GSC tumour growth." (PMID 28569747, 2017).
tumor (continued). "To determine the signalling pathway that mediates the tumour-supportive effect of PTN on GSCs, we examined the expression of the PTN receptor on GSCs." (PMID 28569747, 2017). "Inhibtion of PTN expression led to the reduced subcutaneous tumor growth and metastatis to lung of 1205Lu cells in nude mice." (PMID 28562667, 2017). "The microvessel density was significantly increased in tumour nodules expressing high levels of PTN compared with miR‐384 and control group tumour nodules (P < 0.05)." (PMID 28557334, 2017). "PTN was significantly increased in 47 of 80 (58.75%) tumour tissue samples compared with 15 of 80 (18.75%) matched non‐neoplastic tissue samples and 2 of 20 (10%) normal tissue samples (P < 0.05)." (PMID 28557334, 2017). "We did not detect any tumors in co-injected mice that had lost either the PDGFB cDNA or the PTN cDNA construct, indicating that the combined expression of both genes enhanced tumor formation." (PMID 27806344, 2016). "Our data is consistent with PTN enhancing PDGFB-induced tumor formation through a PTPRz-dependent increase in Akt activation." (PMID 27806344, 2016). "Pleiotrophin (PTN) augments tumor growth by increasing proliferation of tumor cells and promoting vascular abnormalization, but its role in early gliomagenesis has not been evaluated." (PMID 27806344, 2016). "Previous studies revealed that PTN overexpression was detected in many pathologic conditions, including angiogenic, degenerative, inflammatory and neoplastic diseases." (PMID 25617851, 2015). "Different approaches that abrogate constitutive PTN signaling in the malignant cells effectively reverse tumor angiogenesis." (PMID 25617851, 2015). "Not only is PTN involved in tumorigenesis by enhancing the angiogenesis and proliferation of the tumor cells, but it also affects perineural invasion and metastasis by remodeling the malignant cell microenvironment." (PMID 25617851, 2015). "PTN was present in cells at the periphery of the tumour nests, confirming the presence of both ligands within the BCC microenvironment at the protein level." (PMID 24163262, 2013). "Pleiotrophin (PTN) is a heparin-binding growth factor with significant role(s) in tumour growth and angiogenesis." (PMID 22423616, 2012). "PTN or ALK mRNA levels obtained from the tumor specimen were then separated into two groups, i.e., for those patients who were still alive 3 or 5 years after the initial diagnosis versus those patients who had perished by that time." (PMID 23267434, 2012). "The biological effects of PTN-mediated signaling include neurite outgrowth and repair, angiogenesis and mitogenesis of fibroblasts, endothelial and some tumor cell lines." (PMID 23077670, 2012). "The best characterized functions of PTN up to date are those concerning its role(s) in the nervous system, as well as its involvement in tumour growth." (PMID 22423616, 2012). "For this, the respective gene expression arrays of surgical tumor specimen at the time of diagnosis were searched for the levels of PTN or ALK mRNA." (PMID 23267434, 2012). "One interesting target molecule for the treatment of defined tumor entities is the secreted growth factor pleiotrophin (PTN), also known as HB-GAM (heparin biding growth associated molecule) or HARP (heparin affinity regulatory peptide)." (PMID 27721338, 2011). "Antitumor effects based on PTN knockdown demonstrated the advantage of tumor-targeted CRM197-PEG-PEI/siRNA over untargeted PEG-PEI polyplexes." (PMID 27721338, 2011). "When the same strategy was followed in a mouse model, angiogenesis and tumor growth were markedly reduced upon PTN depletion, paralleled by decreased PTN serum levels." (PMID 20714308, 2010). "Consistent with its role in vasculogenesis and tumor agogenesis, PTN expression is also observed in endothelial cells in the developing lung." (PMID 20565841, 2010).
tumor (continued). "PTN functions as an angiogenic factor and promotes remodeling of the tumor microenvironment as well as epithelial-mesenchymal transition (EMT)." (PMID 24281102, 2010). "In the context of defining peptides with anti tumor actions, we sought to identify the minimum sequence responsible for the inhibition of pleiotrophin activity." (PMID 20738847, 2010). "PTN functions as an angiogenic factor and promotes remodeling of the tumor microenvironment and epithelial-mesenchymal transition (EMT)." (PMID 24281102, 2010). "In the context of studying the functions of specific domains of pleiotrophin and defining peptides with anti tumor actions, we identified the minimum sequence responsible for the inhibition of pleiotrophin activity." (PMID 20738847, 2010). "Pleiotrophin mean serum concentrations were 10.8-fold higher in the tumour patient group as compared to the control group (P<0.001)." (PMID 11953815, 2002). "Pleiotrophin exhibits mitogenic and angiogenic properties and has been shown to influence the vascular supply, expansion and metastasis of tumour cells." (PMID 11953815, 2002). "After the growth of implanted human PTN-expressing tumour cells within PTN-negative mice, PTN became detectable in the serum of the mice." (PMID 11953815, 2002). "In the tissue samples of tumour patients from clinical sources, we used multiplex immunofluorescence to confirm that the proportion of NCL + B cells in IBC was significantly higher than that in nIBC, and there was a clear co-localization between PTN + tumour cells and NCL + B cells." (PMID 40624675, 2025). "Moreover, the inflammatory response in turn promotes the malignant progression of tumour cells, and malignant tumour cells upregulate the expression of PTN." (PMID 40624675, 2025). "On the basis of correlation analysis, we propose that HER2 + IBC tumour cells can influence the activation and differentiation process of B cells by upregulating the expression of the heparin-binding growth factor PTN, which in turn promotes the production of TNF by B cells." (PMID 40624675, 2025). "By performing a cellular interaction analysis, we revealed that PTN molecules were significantly overexpressed in HER2 + IBC tumour cells and that the cellular interactions mediated by these molecules were strongly correlated with the functional polarisation of the cellular components in the TME." (PMID 40624675, 2025). "By comparing the expression of PTN in IBC tumour cells of different molecular subtypes, we found that PTN in HER2 + tumour cells had a moderate but significantly higher expression level, and there was a strong correlation between its expression level and the HER2 signature scores." (PMID 40624675, 2025). "Similarly, MDK and PTN, members of the heparin-binding growth factor family, are extensively involved in tumor cell proliferation, EMT, angiogenesis, and immune suppression." (PMID 41383622, 2025). "The multiplex fluorescence results of tumour samples from HER2 + IBC patients also confirmed that PTN was mainly expressed in tumour cells, while NCL had variable expression levels in various cell types, among which B cells and tumour cells were the main high-expression cell types of NCL." (PMID 40624675, 2025). "PTN has been shown to promote tumorigenesis by enhancing cell proliferation and contributing to the tumor microenvironment, while PDGF plays a critical role in angiogenesis and fibrosis associated with tumor progression." (PMID 40722679, 2025). "To verify our hypothesis, we isolated colonic fibroblasts from fresh tumor tissues and treated them with recombinant PTN at indicated time period." (PMID 40069574, 2025). "Notably, PTN enrichment has been observed in the SVZ, where NSCs exhibit tumor-homing properties and likely serve as the primary source of PTN." (PMID 40136662, 2025). "The role of PTN signaling has been well-documented in tumor biology." (PMID 40416874, 2025).
tumor (continued). "Similarly, we found that PTN molecules were significantly overexpressed in HER2 + IBC tumour cells and strongly correlated with tumour EMT and invasive signals, suggesting that PTN molecules play important roles in IBC tumorigenesis and development." (PMID 40624675, 2025). "Consistent with the previous studies, we found that interfering with HER2 could inhibit the phosphorylation of p38 and Erk in HER2 + IBC tumour cells, as well as the expression of PTN." (PMID 40624675, 2025). "Immunohistochemistry experiments for PTN molecules were performed using paraffin samples of clinically sourced HER2 + IBC and nIBC tumour tissues, and we verified at the protein level that the expression of PTN molecules was greater in tumour tissues of IBC origin than in those of nIBC origin." (PMID 40624675, 2025). "Our gene expression analysis of the relevant genes involved in the reciprocal signalling pathways that occur specifically in IBC revealed that the ligand PTN molecule was significantly highly expressed in IBC tumour cells, and its expression was also somewhat elevated in mesenchymal cells." (PMID 40624675, 2025). "Taken together, these data suggest that PTN may partly contribute to stromal remodeling and play a significant role in tumor metastasis." (PMID 40069574, 2025). "Furthermore, blocking the PTN–PTPRZ1 signaling using shRNA or an anti-PTPRZ1 antibody significantly suppressed GBM tumor growth and prolonged animal survival." (PMID 38732975, 2024). "Potentially, PTN-related adaptations that occur in cancer cells during early tumor development may be conserved during metastatic colonization events." (PMID 36828390, 2023). "In our study, increased expression of PTN appeared to correlate with a more aggressive tumor phenotype, which might suggest that PTN could have prognostic value in dogs with PPGL." (PMID 37691636, 2023). "Future in vitro and in vivo studies are warranted to determine whether mentioned drugs (such as DRD2 antagonists, MAPK12 inhibitors, RET inhibitors, or drugs targeting PTN) can inhibit tumor growth and improve survival and quality of life in dogs with PPGL." (PMID 37691636, 2023). "Further, high PTN was associated with lymph node positivity but not with tumor size, age, or hormone status." (PMID 36828390, 2023). "Even though PTN was discovered in the early 1990s, the function of PTN remains unexplored in metastatic breast cancer with the majority of earlier studies reporting its proangiogenic function in primary tumor development." (PMID 36828390, 2023). "PTN levels are negatively correlated with the levels of miR-137 a miRNA that is decreased in hypertrophic scars and of those of miR‐384 a microRNA with potential tumor suppressor activity." (PMID 37484951, 2023). "Moreover, Interference of PTN–PTPRZ1 signaling by shRNA or anti-PTPRZ1 antibody potently suppressed GBM tumor growth and prolonged animal survival." (PMID 35600367, 2022). "In addition, animal studies showed that the PITPNA‐AS1/miR‐223‐3p/PTN axis aided tumor development in vivo." (PMID 35588441, 2022). "Furthermore, the most highly transcribed growth factor in OERCs of MCC14/2—pleiotrophin (PTN)—was reported to be involved in angiogenesis and tumor progression." (PMID 35205840, 2022). "Repression of PITPNA‐AS1 retarded tumor spheres formation, although this impact may be countered by miR‐223‐3p inhibitors or PTN overexpression." (PMID 35588441, 2022). "Disrupting PTN-PTPRZ1 signaling could effectively inhibit GSC-driven tumor development, and this result meant that targeting PTN-PTPRZ1 signaling therapy could enhance treatment for GBM and other malignant tumors." (PMID 34368156, 2021). "Cell surface nucleolin serves as a binding partner of different molecules (as P-selectin, hepatocyte growth factor or pleiotrophin), thus mediating their biological activities, such as cell differentiation, adhesion and leukocyte trafficking, inflammation, angiogenesis and tumor development." (PMID 34207464, 2021).